MCL1 (MCL1 apoptosis regulator, BCL2 family member)
Diseases named in the same sentence as MCL1 in open-access papers (continued):
Sharing a sentence is not in itself a finding about the gene and the disease.
cancer (continued). "Myeloid cell leukemia-1 (Mcl-1) belongs to the BCL-2 family and regulates apoptosis in normal and cancer cells." (PMID 30086763, 2018). "Whereas LIF does not affect cell proliferation or invasion of cancer cells, it protects malignant cholangiocytes from chemotherapy-induced apoptosis via a STAT3- and MAPK-independent, PI3K/AKT-dependent Mcl-1 activation." (PMID 26296968, 2015). "For example, various transcriptional inhibitors induce the downregulation of anti-apoptotic proteins, such as Mcl-1, XIAP and survivin, or oncogenes, such as MYC, without disrupting the transcription of normal genes in cancer cell lines." (PMID 24576043, 2014). "Owing to the low affinity with the apoptotic factor Mcl-1, the BH3 mimetic drug ABT-737 failed to exert potent cancer-killing activities in variety of cancer models including HCC." (PMID 23284992, 2012). "Surprisingly, we found that upon vincristine treatment there were no significant changes in the anti-apoptotic proteins MCL-1, BCL-xL, or BCL-2 expression, indicating that cancer cells’ adaptation to this therapy relies on different mechanisms other than increased expression of these proteins." (PMID 32801295, 2020). "Interestingly, anthracyclines have been reported to provoke Mcl-1 downregulation and thereby synergizing with ABT-263, a non-selective Bcl-2/Bcl-xL inhibitor to kill cancer cells." (PMID 32943617, 2020). "While MCL1, BCL2L1, or BCL2L2 were ubiquitously expressed, BCL2 and BCL2A1 demonstrated tissue/lineage-selective expression with very low/no expression across most of the cancer cell lines and TCGA tumor tissues." (PMID 30635584, 2019). "However, in contrast to normal cells where JNK-induced phosphorylation of Mcl-1 at Thr163 targets it for degradation via the GSK3 pathway, Mcl-1 is not degraded via this pathway in cancer cells." (PMID 28301598, 2017). "In addition it has been reported that USP9X influences cell apoptosis by stabilizing MCL-1, but the USP9X substrate that takes part in regulation of cell proliferation and cancer progression had not heretofore been identified." (PMID 27517496, 2016). "The fact that miR-29 family members are often not expressed in cancer cells could be crucial for cancer control: miR-29 down-regulates important genes such as CDC42, TCL-1 and MCL-1, which normally confer tumor-suppressing traits." (PMID 23245396, 2012). "Notably, we did not detect any MCL-1 amplification in our cohort which could potentially correlate with MCL-1 dependency, thereby promoting, for instance, cancer survival and drug resistance." (PMID 39912943, 2025). "Screening of FDA-approved anti-cancer drugs in chemoresistant cells identified therapeutics that may be beneficial in combination with the clinically tested BH3-mimetic ABT263, but no synergistic drug interactions with the selective MCL1 inhibitor S63845." (PMID 37723317, 2023). "Regardless of the different phenotypes of the two cancer cell types, T3 decreased the levels of anti-apoptotic proteins (cIAP1, cIAP2, XIAP, cFLIP and Mcl-1) for a short period of exposure and altered the splicing of the anti-apoptotic MCL1L and CFLAR isoform in A2780 and HCT116 cells." (PMID 33064779, 2020). "These suggest that down-regulation of Mcl-1 protein expression may be necessary, but not sufficient for induction of apoptosis, whereas CDK9-targeted transcriptional inhibition of Mcl-1 should be more effective apoptotic strategy in cancer cells." (PMID 25277198, 2014). "In addition to phosphorylation of BAD at S112 and s136, Mcl1 (or CREB) activated by stress signaling could also inhibit apoptotic, so percent apoptosis in cancer cells was decreased compared to the no-stress condition." (PMID 24339759, 2013). "However, cancer cells relying on BCL2 and lacking MCL1/BCL2L1 might also be more resistant to CGs." (PMID 37904054, 2024).
tumor (1,038 papers, 1999 to 2026). "Consistently, we found the MCL1 expression was also elevated in the patient's tumor sample harboring the FBW7 R465C mutation compared to the wild‐type counterpart (p < 0.05)." (PMID 41312772, 2025). "The upregulation of MCL‐1 has been observed in a wide range of tumor cells and is linked to chemotherapeutic resistance in a broad range of cancers." (PMID 40970582, 2025). "MCL1 inhibitors suppress mTORC1 in tumor cells but are associated with cardiotoxicity due to mTORC1 inhibition in the heart." (PMID 41326406, 2025). "There is evidence indicating that an elevated level of MCL‐1 is associated with tumor resistance to venetoclax and navitoclax." (PMID 40970582, 2025). "Although the frequency of SF mutation in MM is relatively low, a potent anti-tumor activity of splicing modulators was found to be linked with a remarkable change in the MCL1 spliced variants usage in treated cells than controls." (PMID 39528914, 2024). "We have previously found that BCL2A1 is associated with decreased sensitivity to MCL1 inhibition in tumor cells." (PMID 38459020, 2024). "The high MCL-1 expression group demonstrated shorter disease-free and overall survival times and was statistically associated with tumor size, Ki-67 expression, and metastasis." (PMID 39012900, 2024). "We have previously shown that overexpressing BCL2A1 in tumor cells make them less susceptible to MCL1 inhibitor." (PMID 38459020, 2024). "It has been established that MCL-1 protein degradation is compromised observed subsequent to FBXW7 mutation or deletion within tumor cells, leading to resistance to anti-microtubule drugs such as paclitaxel and vincristine." (PMID 38027013, 2023). "We then characterised the mutational signatures of tumours arising from Mcl-1 deficiency to compare them with human COSMIC signatures, and where possible, to assign them to known molecular aetiologies." (PMID 37663116, 2023). "Overexpression of the MCL-1 protein or amplification of the MCL1 gene has been observed in multiple tumor types, where it is associated with tumorigenesis and poor prognosis." (PMID 37880389, 2023). "Cd47 knockdown induced phagocytosis and antigen presentation, and knockdown of Cd274 and Mcl1 reduced checkpoint inhibition and caused tumor cell death, respectively." (PMID 36969696, 2023). "We and others have showed the association of MCL1 and Bcl-xL expression with tumor progression and survival in solid tumors including CRC." (PMID 35042842, 2022). "The analysis revealed that BCL2L1 (BCL-xL) and MCL-1 were exclusively expressed in tumour regions marked by the hallmark chromosomal alterations, namely gain in chromosome 7 and loss of chromosome 10." (PMID 35473984, 2022). "Repression of MCL-1 in MM cells is associated with protein translation inhibition, and is coupled with tumor sensitivity to the ER stressor thapsigargin, which is able to induce mitochondrial apoptosis through MCL-1/Bak interaction." (PMID 36358759, 2022). "Myeloid Cell Factor 1 (MCL1) encodes an antiapoptotic protein that most MM tumors depend on for survival through both tumor-intrinsic and extrinsic mechanisms." (PMID 35912171, 2022). "Mutations in the tumor suppressor FBW7 causes elevated levels of Mcl-1 which in turn contributes to resistance against the multi-kinase inhibitor regorafenib in colorectal cancer (CRC) patients." (PMID 36045907, 2022).
tumor (continued). "The finding that MCL-1, an inhibitor of apoptosis, and BCL-2 levels are modulated by the tumor-associated microenvironment has stimulated further investigation focused on MCL-1 inhibition." (PMID 36212502, 2022). "Studies on the associations between Mcl-1 overexpression and advanced tumor stages and lymph node metastasis are limited." (PMID 35524332, 2022). "Taken together, these results indicated that high levels of serum leptin and pSTAT3/CEBPD/MCL1 axis activation were significantly associated with advanced clinical stages and tumor grades." (PMID 34156978, 2021). "Overexpression of MCL-1 is frequently observed in many tumor types and is closely associated with tumorigenesis, poor prognosis and drug resistance." (PMID 33883020, 2021). "Instead, in MM where plasma cells are terminally differentiated it acts via the interaction with different targets such as Myeloid cell leukemia-1 (MCL-1), an inhibitor of apoptosis, to cause drug resistance in different tumor diseases." (PMID 33672466, 2021). "In a range of hematological and solid cancers, MCL-1 has been implicated in tumor formation, cell survival, and treatment resistance, including resistance to BCL-XL and BCL-2 targeting." (PMID 35008216, 2021). "In this way, fragments of WT and Mcl1fl/fl (MCL-1 proficient) tumours were engrafted into the mammary fat pad of multiple WT recipients and allowed to establish before tamoxifen induction to delete both alleles of Mcl1 in Mcl1fl/fl tumours." (PMID 33785871, 2021). "Our results demonstrate that CYC065 and THZ1 inhibit tumour cell growth and induce caspase-dependent apoptotic cell death, associated with the downregulation of the anti-apoptotic protein Mcl-1." (PMID 34344865, 2021). "Studies in other tumor types have reported that dinaciclib reduces Mcl-1 expression, causing Mcl-1-dependent apoptosis." (PMID 33800911, 2021). "These tumor clones are highly sensitive to MCL-1 inhibition, which is linked to decreased oxidative phosphorylation, thus overcoming unmet medical needs in AML." (PMID 33308268, 2020). "FBW7, a tumor suppressor and E3 ubiquitin ligase of Mcl-1, is frequently mutated in CRCs, which underlies intrinsic regorafenib resistance in CRC cells." (PMID 32724460, 2020). "Up-regulation of Mcl-1 has been linked to advanced stage of tumor pathology and metastasis while c-FLIP overexpression significantly correlates to shorter survival in NSCLC patients." (PMID 32069989, 2020). "Dysregulated proliferation is a significant hallmark of tumor cells, and the regulatory factors include antiapoptotic proteins (e.g., Bcl-xL, and Mcl-1) and proliferation regulatory proteins (e.g., cyclin D1, Myc, and survivin)." (PMID 32957082, 2020). "Our data demonstrated that ectopic expression of miRNA-101 was associated with suppression of Mcl-1 mRNA in tumor cells." (PMID 32212793, 2020). "Overexpression of anti-apoptotic proteins such as Bcl-2, Bcl-XL, and Mcl-1 has been associated with drug resistance in human tumor cell lines, including NHL cells." (PMID 31798573, 2019). "Our integrate approach revealed a profound effect of MYC overexpression on tumor evolution and identified MCL1 as a critical and druggable dependency in BRCA1-deficient TNBC with high expression of MYC." (PMID 30674894, 2019). "Recent studies have shown that loss of FBXW7 function causes therapeutic resistance through the accumulation of several oncoproteins associated with tumor progression and therapeutic resistance, including cyclin E, c-Myc, c-Jun, Notch and MCL1." (PMID 31067777, 2019). "The authors showed that modulation of ERK-dependent Bim and Mcl-1 degradation are critical for anti-tumor activity in NSCLC harboring EGFR-activating mutations." (PMID 29641535, 2018). "From this discussion it can be inferred that a higher expression of Bax, Bak, Bim, or Bad is likely to confer tumor cells a survival advantage, whereas an increased expression of Bcl-2, Bcl-xL, or Mcl-1 is likely to be associated with a poorer prognosis." (PMID 30486451, 2018).
tumor (continued). "USP9X can stabilize MCL1 by removing the Lys 48-linked polyubiquitin chains, which normally mark MCL1 for degradation and thereby promote tumor cell survival." (PMID 28938551, 2017). "In IDH1-mutated tumor samples Mcl-1 expression was significantly decreased, suggesting a broad biological applicability of this observation." (PMID 29057925, 2017). "A subset of tumour cell lines exhibit dependence on MCL1 expression for survival and this dependence is also associated with tumour response to HSP90 inhibition." (PMID 26096930, 2016). "Myeloid cell leukemia-1 (MCL-1) is a potent survival factor for normal and malignant tissues and is associated with chemo-resistance in a wide range of tumor types." (PMID 27931239, 2016). "The anti-tumor drug actinomycin D caused less cell death and caspase-3/7 activation in Bcl-2-, Mcl-1- or Bcl-xL-overexpressing cells than in cells expressing the empty vector." (PMID 26758417, 2016). "Reduced MCL-1 levels due to sorafenib exposure have been linked in many tumor types to increased levels of apoptosis." (PMID 27015562, 2016). "These inhibitors are however ineffective against MCL-1, which is commonly amplified in human tumours and associated with tumour relapse and chemoresistance." (PMID 26059440, 2015). "USP9X can stabilize MCL-1 to promote tumor cell survival through removing the Lys 48-linked polyubiquitin chains that normally mark MCL-1 for proteasomal degradation, which serves as a prognostic and therapeutic target of human malignancies." (PMID 26097878, 2015). "Dinaciclib caused significant tumor regression (%TGI = 191%) in the MCL1:BCL-xL high mRNA ratio and MCL1-dependent NCI-H23 xenograft model." (PMID 25289887, 2014). "Our results therefore provide evidence supporting the rationale for therapeutic strategies targeting both OPN and Mcl-1 to interrupt associated anti-apoptotic signaling in drug-resistant GIST for prevention of tumor progression." (PMID 24947165, 2014). "They found USP9X knockdown alone caused a modest decrease in tumour growth but specifically stabilized MCL1 by removing its degradative Lys 48-linked polyubiquitin chains to promoting cell survival." (PMID 24152793, 2013). "Here we show that over-expression of Mcl-1 in pancreatic patient tumor samples is linked to advancement of the disease." (PMID 24025188, 2013). "NF-κB upregulates the expression of a number of genes implicated in facilitating tumor cell survival, such as Mcl-1, Bcl-2, Bcl-XL, c-IAP1, c-IAP2, FLIP and survivin." (PMID 24146961, 2013). "Animals treated with doses of Minnelide shown to cause tumor regression show a decrease in levels of Mcl-1 and increase in miR-204 expression compared to saline treated controls." (PMID 24025188, 2013). "Our results show that ascites induce a rapid activation of Akt and ERK1/2 but only that ERK1/2 activation is associated with Mcl-1 upregulation in tumor cells." (PMID 23158473, 2012). "Activated STAT3 has been shown to protect tumour cells from apoptosis by regulating genes encoding antiapoptosis-associated proteins, such as Bcl-2, Bcl-xl, and Mcl-1." (PMID 20461084, 2010). "Importantly, high MCL1 RNA levels in tumour tissue were associated with poorer survival in these patients." (PMID 41505030, 2026). "Our Co‐IP assays demonstrated markedly reduced FBW7 R465C‐MCL1 binding compared to wild‐type FBW7, leading to impaired degradation and consequent upregulation of MCL1 in R465C‐mutated patient‐derived CRC tumor tissues and experimental models, which is consistent with the previous finding." (PMID 41312772, 2025). "Higher MCL-1 expression was significantly associated with metastasis and tumor size." (PMID 40380182, 2025).
tumor (continued). "A high MCL-1 expression in canine MGT has been associated with larger tumor size and metastasis." (PMID 40380182, 2025). "We further detected the levels of Ki-67, a well-known cell proliferation marker; cleaved PARP (cPARP), a hallmark of apoptosis; and Bim and Mcl-1, 2 critical apoptosis-regulating proteins modulated by the combinations in tumor tissues receiving these treatments." (PMID 38451729, 2024). "Furthermore, this study confirmed a significant association between high MCL-1 expression and previously considered clinical indicators of poor prognosis, such as Ki-67 levels exceeding 15% and tumor size larger than 3 cm." (PMID 39012900, 2024). "MCL-1(myeloid cell leukemia sequence 1) overexpression on tumor plasma cells, associated with amplifications of chromosome 1q21, could be a possible therapeutic target with MCL-1 inhibitors." (PMID 36900299, 2023). "Knockdown of the PD-L1 gene in preclinical studies was associated with increased levels of BCL-2 and MCL-1 in lymphocytes T, which could increase their survival and promote tumor apoptosis." (PMID 36902139, 2023). "In addition, MCL1 copy number gain (2.1), low tumor mutation burden and stable microsatellites, were also confirmed." (PMID 38239638, 2023). "Due to the specific binding between CP7 and A549 cells, siRNA-loaded liposome-PEG-CP7 showed increased cellular uptake in vitro, resulting in significant apoptosis of tumor cells through silencing of the Mcl-1 gene, which is associated with apoptosis and angiogenesis." (PMID 35955516, 2022). "Interestingly, previous research has linked kaempferol’s anti-tumour effect to Bcl-2 family proteins that regulate the endogenous mitochondrial apoptosis pathway, which can downregulate Bcl-2 and Mcl-1 while increasing Bax protein expression." (PMID 36386146, 2022). "Similarly, loss of a single Mcl-1 allele also delayed tumor onset and impaired the survival of T-cell lymphomas developed in a T lymphocyte non-Hodgkin’s lymphoma (T-NHL) mouse model driven by the fusion kinase ITK-SYK signaling." (PMID 34336857, 2021). "Tumor cell death caused by SEL120-34A was mediated by MCL1 transcriptional silencing." (PMID 34298959, 2021). "Nocodazole, another anti-helmenthic, inhibited tumor growth via cell cycle arrest and microtubule dysfunction, associated with increased Bim and myeloid cell leukemia-1 (MCL-1) expression and c-Jun NH2-terminal kinase (JNK)-mediated B cell lymphoma protein-2 (BCL-2) phosphorylation." (PMID 36046752, 2021). "Several mechanisms of resistance to venetoclax have been reported involving the up-regulation of antiapoptotic molecules Mcl-1 and Bcl-xL, mutations in genes controlling different kinase pathways, transcription factors, epigenetic modifiers, and tumor suppressors." (PMID 34771453, 2021). "As up-regulation of Mcl-1 and Bcl-2 is associated with proliferation and survival of the tumor cells; we therefore sought to assess whether miRNA-15a could inhibited the proliferation of CLL cells." (PMID 34319043, 2021). "Furthermore, homozygous loss of Mcl1, specifically in the tumour epithelium, provoked tumour regression and allowed long-term tumour-free survival." (PMID 33785871, 2021). "Blocking Mcl-1 makes tumour cells more susceptible to anticancer agents." (PMID 33557839, 2021). "Thus, it is likely that there is a selection against Mcl-1 loss in Eμ-Myc tumors, which suggests Mcl-1 dysregulation is prerequisite for tumor development in this model." (PMID 34336857, 2021).